ELANE (elastase, neutrophil expressed)
Diseases named in the same sentence as ELANE in open-access papers (continued):
Sharing a sentence is not in itself a finding about the gene and the disease.
psoriasis (19 papers, 2016 to 2026). An autoimmune condition characterized by red, well-delineated plaques with silvery scales that are usually on the extensor surfaces and scalp. "An additional correlation of ULK1 with other granule-derived antimicrobial peptides and enzymes, including Cathelicidin (LL37) and elastase (ELANE), was found exclusively in psoriasis patients but not health donors." (PMID 34421918, 2021).
diabetes (17 papers, 2016 to 2025). "Cathepsin G (CTSG) and neutrophil elastase (ELANE), were both found to be secreted by neutrophils and play an important role in promoting inflammatory response and vascular endothelial cell permeability, which was closely related to the pathophysiology of diabetes." (PMID 40641746, 2025).
leukemia (17 papers, 2012 to 2025). A malignant (clonal) hematologic disorder, involving hematopoietic stem cells and characterized by the presence of primitive or atypical myeloid or lymphoid cells in the bone marrow and the blood. "Early HSCT is also known to lower the risk of leukemia development in patients with the ELANE defect." (PMID 41383606, 2025). "SCN can be a pre-leukemic syndrome with evolution to leukemia recognized in patients with ELANE and HAX1 variants, as well as X-linked neutropenia (WAS)." (PMID 32066420, 2020). "As demonstrated in our studies, patients with the ELANE gene defects may develop symptoms at a later age or learn about the mutation during family tests or after developing leukemia." (PMID 41383606, 2025). "In light of this, the authors proposed that ELANE serves as an oncogene driving leukemia development." (PMID 40338916, 2025). "To study antigen-specific T cells in CML, we chose PR1, a leukemia-associated antigen from proteinase 3 (PRTN3) and neutrophil elastase (ELANE) genes, as anti-PR1 T cells have been associated with response to TKI and successful IFN-α discontinuation." (PMID 37919606, 2024). "Unfortunately, in leukemia patients, ELANE is highly expressed and predicts poor survival." (PMID 38967692, 2024). "G-CSF could modify the activation of target protein, so it might bind with ELANE to activate ELANE and subsequently induce pyroptosis in leukemia cells." (PMID 35768562, 2022). "Mechanistically, G-CSF induced pyroptosis through ELANE in leukemia cells." (PMID 35768562, 2022). "We selected five AML cases with high, intermediate, or low expression of one of the major neutrophil serine proteases, ELANE and, as a negative control, a human leukemia cell line (K562) that does not express ELANE." (PMID 38219859, 2024). "In the context of hematologic malignancies, our study revealed that ELANE expression is significantly elevated in AML samples relative to healthy controls and correlates with poorer overall survival, thereby supporting its role as a prognostic biomarker in leukemia." (PMID 40748972, 2025).
atherosclerosis (14 papers, 2014 to 2025). A disease characterized by the build-up of fatty material and calcium deposition in the arterial wall resulting in partial or complete occlusion of the arterial lumen. "The LAA mechanism clots demonstrated elevated levels of proteins such as CD59, LAMP1, and ELANE, which are associated with the ubiquitin‐proteasome pathway and the progression of atherosclerosis." (PMID 40079446, 2025). "In this group of genes we observed correlation between the cytokine IL10 and ELANE, an elastin protease known to degrade elastic fibers as elastin; indicating that elastin degradation and immune response process are common interacting regulatory mechanisms in atherosclerosis." (PMID 25503069, 2014).
colitis (14 papers, 2015 to 2025). Inflammation of the colon. "Given the suggested role of ELANE in colitis-induced growth attenuation observed in this study, future incorporating ELANE inhibitors into treatment strategies for children with inflammation-related growth failure may be a promising novel approach." (PMID 41409609, 2025). "The most important finding of this work is the identification of ELANE in chondrocytes of the EGP and its involvement in growth attenuation during DSS induced colitis." (PMID 41409609, 2025).
viral infection (13 papers, 2016 to 2026). "We also analyzed genes associated with formation of NETS34,35: ELANE (neutrophil elastase) and MPO (myeloperoxidase) were elevated in MIS-C in comparison with viral infection (ELANE only) and KD." (PMID 39300098, 2024). "PRTN3, ELANE and CSTG were significantly increased in all three viral infection cohorts." (PMID 33868254, 2021). "However, SNVs in other proteases, including ELANE, have not been previously reported in patients with this viral infection." (PMID 38226800, 2024).
pneumonia (12 papers, 2013 to 2024). An acute, acute and chronic, or chronic inflammation focally or diffusely affecting the lung parenchyma, caused by an infection in one or both of the lungs (by bacteria, viruses, fungi, or mycoplasma.). "According to Gene sequencing and other tests, the patient was diagnosed with SCN caused by ELANE gene mutation, severe pneumonia, Mycobacteriosis abscess, nutritional iron deficiency anemia, multiple abscesses of the skin, hypergammaglobuloemia, and thrush." (PMID 36343040, 2022). "The top 50 over-abundant transcripts in pneumonia were dominated by antimicrobial neutrophil-related genes e.g ELANE, DEFA1B, MMP8, CAMP, DEFA3, DEFA4, MPO, LTF." (PMID 23940611, 2013).
Arthritis (11 papers, 2010 to 2025). Inflammation of a joint. "According to literature, ELANE mutations can be associated with arthritis and pyoderma gangrenosum, but all of such mutations were reported as individual cases." (PMID 37118811, 2023). "Moreover, double knockout mice for ELANE and Ctsg demonstrated a reduced arthritis score compared to wild-type mice, which further demonstrates the role of these enzymes in disease progression." (PMID 41409609, 2025).
pancreatic cancer (11 papers, 2011 to 2025). "Interestingly, the high ELANE expressers tended to group together in the unsupervised cluster analysis of pancreatic cancer proteins identified with tryptic peptides (highlighted with box)." (PMID 38219859, 2024).
systemic lupus erythematosus (11 papers, 2020 to 2025). An autoimmune multi-organ disease typically associated with vasculopathy and autoantibody production. "Furthermore, we identified neutrophils in cutaneous lesions of DLE and SLE by immunofluorescence staining for ELANE (a neutrophil elastase), suggesting that neutrophils are involved in the formation of cutaneous lesions of lupus." (PMID 36470882, 2022). "Therefore, to further probe the hypothesis that NETs drive lupus, we decided to genetically target the serine protease elane, since multiple studies both directly and indirectly implicate ELANE in NET formation in mice and humans." (PMID 32243431, 2020). "Taken together with earlier work, these findings add additional evidence that challenges the concept that neutrophils and NETs, to the degree that NET generation and neutrophil effector function relies on PADI4, ELANE, or CYBB, critically drives lupus." (PMID 32243431, 2020). "Villanueva and colleagues showed an enhanced expression of proteins linked to neutrophil antimicrobial activity in systemic lupus erythematosus (SLE) [e.g., myeloperoxidase (MPO), neutrophil elastase (ELANE), alpha defensin 4 (DEFA4)]." (PMID 38596677, 2024). "Our work adds ELANE to the list of CYBB and PADI4 as proteins that are required for NET formation, yet are not needed for lupus." (PMID 32243431, 2020).
rheumatoid arthritis (9 papers, 2019 to 2025). A chronic, systemic autoimmune disorder characterized by inflammation in the synovial membranes and articular surfaces. "ELANE inhibitors, currently under investigation as potential therapies for osteoarthritis and rheumatoid arthritis, help preserve cartilage by limiting MMP activity." (PMID 41409609, 2025). "The role of ELANE in cartilage degradation and bone re-modelling has been well-established in rheumatoid arthritis and osteoarthritis (OA), but its expression in chondrocytes of the EGP and its involvement in growth attenuation during IBD is a novel contribution of this study." (PMID 41409609, 2025).
acute myeloid leukemia (7 papers, 2017 to 2025). Acute myeloid leukemia (AML) is a group of neoplasms arising from precursor cells committed to the myeloid cell-line differentiation. "It has been reported that SCN caused by ELANE mutations can lead to myelodysplastic syndromes (MDS) or acute myeloid leukaemia (AML)." (PMID 37118811, 2023). "Opinions are divided as to the risk of malignant transformation; however, the most recent evidence indicates that the development of acute myeloid leukemia is increased in patients harboring ELANE mutant." (PMID 33968054, 2021). "This study represents an important step toward the development of alternative therapies for patients with ELANE mutations, particularly those who respond poorly to G-CSF and are at increased risk of progression to myelodysplastic syndrome (MDS) and acute myeloid leukemia (AML)." (PMID 39867870, 2024).
lung adenocarcinoma (7 papers, 2014 to 2025). A carcinoma that arises from the lung and is characterized by the presence of malignant glandular epithelial cells. "Using the LSK-K-ras mouse model of lung adenocarcinoma as an example, it was shown that mice lacking the ELANE gene (encoding neutrophil elastase) had a higher surface survival rate compared to ELANE (+) mice." (PMID 36613577, 2022).
malaria (7 papers, 2013 to 2025). Malaria is a serious and sometimes fatal disease caused by a parasite that commonly infects a certain type of mosquito which feeds on humans. "ELANE encodes for neutrophil elastase, a protein previously associated with retinopathy-positive cerebral malaria and undifferentiated severe malaria in comparison to unmatched controls with mild disease." (PMID 40383794, 2025). "Transcripts of genes encoding neutrophil granule protein MPO and ELANE were expressed at higher levels in concurrent CM and SMA in comparison to uncomplicated malaria, and separately in comparison to cases of CM alone." (PMID 40383794, 2025). "It has been reported that the neutrophil granule proteins MMP8, OLFM4, DEFA3, and ELANE are increased in severe malaria versus uncomplicated malaria." (PMID 36380373, 2022).
thrombosis (7 papers, 2018 to 2023). "In this study, elane-deficient mice formed NETs in an experimental model of deep venous thrombosis (DVT) and ELANE deficiency did not protect mice from DVT in this model." (PMID 32243431, 2020).
autoimmune disease (6 papers, 2019 to 2025). A disorder resulting from loss of function or tissue destruction of an organ or multiple organs, arising from humoral or cellular immune responses of the individual to their own tissue constituents. "In this study, we reported three cases of ELANE mutations with associated autoimmune diseases such as SLE, AIHA, and ANCA-associated small vasculitis respectively." (PMID 37118811, 2023). "Three cases of children with ELANE mutations manifesting as autoimmune diseases, who were under treatment from April 2020 to May 2021, were retrospectively analysed." (PMID 37118811, 2023). "Patients with ELANE mutations, combined with autoimmune diseases, may have recurrent infections." (PMID 37118811, 2023).
influenza (6 papers, 2019 to 2024). An acute viral infection of the respiratory tract, occurring in isolated cases, in epidemics, or in pandemics; it is caused by serologically different strains of viruses (influenzaviruses) designated A, B, and C, has a 3-day incubation period, and usually lasts for 3 to 10 days. "Our integrated analysis and validation results also again illustrate that these candidate genes, including ELANE, DEFA4, involved in NETs formation, could cause or participate in the process of severe influenza." (PMID 33448094, 2021). "The concentrations of the RETN, MMP8, LCN2, ELANE and BPI in plasma tended to be higher in influenza patients than healthy donors." (PMID 33448094, 2021). "In comparison, three patients had high activation of only a subset of influenza-connected genes PRTN3, LTF, PGLYRP1, DEFA1B, DEFA1, DEFA4, ELANE, and MPO." (PMID 34335605, 2021). "Area under the curve (AUC) analysis of ROC showed that LCN2, BPI, ELANE and MMP8 expression represented severe influenza infection." (PMID 33448094, 2021).
myelodysplastic syndrome (6 papers, 2023 to 2025). A clonal hematopoietic disorder characterized by dysplasia and ineffective hematopoiesis in one or more of the hematopoietic cell lines. "Patients harboring the ELANE mutation may experience the onset of myelodysplastic syndrome (MDS), AML, or, in rarer cases, acute lymphoblastic leukemia (ALL)." (PMID 40338916, 2025). "Overall, 16 patients (17.2%) had pathogenic variants, including FANCA, BRCA2, PMS2, ELANE, G6PC3 and VPS13B in patients with idiopathic neutropenia, and GATA2 in patients with suspected myelodysplastic syndrome." (PMID 40358701, 2025). "Whole-genome sequencing (WES) of peripheral blood did not detect mutations in the ELANE or GATA2, typically associated with cyclic neutropenia or myelodysplastic syndrome (MDS)." (PMID 39781543, 2024).
ovarian carcinoma (6 papers, 2003 to 2022). A malignant neoplasm originating from the surface ovarian epithelium. "provided a novel gene signature including 7 PRGs (AIM2, PLCG1, ELANE, PJVK, CASP3, CASP6, and GSDMA) for predicting the prognosis of ovarian cancer (OC) patients and laid a foundation for further studies of the relationships between PRGs and immunity in OC." (PMID 35912258, 2022).
periodontal disease (6 papers, 2017 to 2024). "They observed that patients with pathogenic variants in ELANE present with more severe periodontal disease than patients with HAX1 or unknown genetic defects." (PMID 32625202, 2020).
colorectal cancer (5 papers, 2013 to 2025). A primary or metastatic malignant neoplasm that affects the colon or rectum. "Additionally, our analysis of data obtained from The Cancer Genome Atlas (TCGA) database revealed that ELANE gene expression is higher in normal tissues than in tumor tissues and that colorectal cancer patients with high ELANE expression have a better prognosis." (PMID 40082916, 2025).
endotoxemia (5 papers, 2019 to 2022). "Similar patterns were observed for the relative expression of the neutrophil markers ELANE and MPO after the induction of endotoxemia, except in the spleen." (PMID 31817302, 2019).
acute kidney injury (4 papers, 2015 to 2024). Sudden and sustained deterioration of the kidney function characterized by decreased glomerular filtration rate, increased serum creatinine or oliguria. "Moreover, elevated ELANE levels in the blood are linked to various clinical factors, including ICU admission, body temperature, lung damage, cardiovascular markers, and renal failure." (PMID 38226800, 2024).
Autoimmunity (4 papers, 2017 to 2025). The occurrence of an immune reaction against the organism's own cells or tissues. "However, ELANE deficiency did not alter the anti-self response nor clinical parameters of SLE in the MRL.Faslpr model, ruling out one possible source of proteases that could fuel such a mechanism of loss of tolerance in autoimmunity." (PMID 32243431, 2020).
chronic granulomatous disease (4 papers, 2019 to 2025). Chronic granulomatous disease (CGD) is a rare primary immunodeficiency, mainly affecting phagocytes, which is characterized by an increased susceptibility to severe and recurrent bacterial and fungal infections, along with the development of granulomas. "Neutrophils of patients with mutations in the neutrophil elastase gene ELANE demonstrated global proteome dysregulation, whereas chronic granulomatous disease and leukocyte adhesion deficiency had modest effects on the respective neutrophil proteomes." (PMID 30630937, 2019).
colon carcinoma (4 papers, 2011 to 2026). "These public colon cancer datasets showed a statistically significant association between BDNF and two neutrophilic markers, CD66b and neutrophil elastase (ELANE)." (PMID 34771682, 2021).
Neonatal sepsis (4 papers, 2011 to 2025). Systemic inflammatory response to infection in newborn babies. "Hence, the lower methylation levels observed in the promoters of genes involved in neutrophil activation (i.e., ATP8B4, LRG1, TREM1, PRTN3, S100A8, ELANE, and CD177) illustrates the role of DNAm in innate immunity in neonatal sepsis." (PMID 33659006, 2021).
acute promyelocytic leukemia (3 papers, 2015 to 2024). An aggressive form of acute myeloid leukemia (AML), characterized by arrest of leukocyte differentiation at the promyelocyte stage, due to a specific chromosomal translocation t(15;17) in myeloid cells. "In contrast to these studies of NE-regulated suppression of cancer, ELANE is expressed in promyelocytic leukemia (PML) and sustains PML by inhibiting apoptosis via degradation of BAX a pro-apoptotic protein and upregulation of Bcl-2, an apoptosis inhibitor." (PMID 39684750, 2024).
cerebral malaria (3 papers, 2018 to 2025). A sequestration of Plasmodium falciparum in the brain, which can cause coma and/or seizures. "The five identified proteins (ANK1, CD14, CDK14, ELANE, MPP1) were found to be elevated in the febrile convulsion group compared to cerebral malaria." (PMID 30442134, 2018).
clear cell renal cell carcinoma (3 papers, 2020 to 2022). "Another large-scale DNA methylation transcriptome analysis also identified the neutrophil-expressed elastase (ELANE) as a vital biomarker associated with the invasion and metastasis of clear cell renal cell carcinoma (ccRCC)." (PMID 35756629, 2022). "And ELANE has been identified as a novel methylation prognostic signatures for clear cell renal cell carcinoma." (PMID 33299888, 2020). "Scholars found that the ELANE gene may be related to the invasion and metastasis of clear cell renal cell carcinoma and is a potential prognostic and therapeutic marker of clear cell renal cell carcinoma." (PMID 34876094, 2021).
dengue (3 papers, 2016 to 2025). "Previous transcriptomic analysis of patient PBMCs identified increased expression of RNA transcripts involved in mitochondrial processes and neutrophil-associated enzymes (MO, ELANE) in severe dengue." (PMID 40573396, 2025).
liver disease (3 papers, 2015 to 2025). "Recent mechanistic studies have shown that ELANE promotes KEAP1 protein stability, inhibiting NRF2‐mediated ferroptosis in metabolic dysfunction–associated steatotic liver disease." (PMID 40895144, 2025).
osteoarthritis (3 papers, 2021 to 2025). A noninflammatory degenerative joint disease occurring chiefly in older persons, characterized by degeneration of the articular cartilage, hypertrophy of bone at the margins and changes in the synovial membrane. "ELANE plays key roles in degenerative and inflammatory diseases through the proteolysis of collagen-IV and elastin, and has been implicated in osteoarthritis." (PMID 36890868, 2023).
parasitic infections (3 papers, 2022 to 2025). "Furthermore, ELANE and GZMM have also been demonstrated in African N’Dama cattle, depicting multiple biological functions in parasitic infections." (PMID 35391795, 2022).
triple-negative breast carcinoma (3 papers, 2022 to 2025). An invasive breast carcinoma which is negative for expression of estrogen receptor (ER), progesterone receptor (PR), and human epidermal growth factor receptor 2 (HER2). "Similarly, exosomes modified with α-lactalbumin (α-LA) delivered human neutrophil elastase (ELANE) and the Toll-like receptor 3 (TLR3) agonist Hiltonol, both inducers of immunogenic cell death, to triple-negative breast cancer (TNBC) models." (PMID 39961904, 2025).